SETD2 (SET domain containing 2, histone lysine methyltransferase)
Diseases named in the same sentence as SETD2 in open-access papers (continued):
Sharing a sentence is not in itself a finding about the gene and the disease.
tumor (continued). "For example, SETD2 (the only enzyme that performs K36me2 to me3 modification) is mutated in renal carcinoma and breast cancer, and NSD2, which generates K36me2, has been shown to be a tumor suppressor." (PMID 25773741, 2015). "Thus, based on the binomial calculation, in order to detect a mutation in PBRM1, SETD2, BAP1, and/or KDM5C with 90% certainty, a tumor would need to be genetically profiled in at least three locations." (PMID 25124064, 2014). "The tumor with the most mutated genetic landscape contained a shared SETD2 mutation and four nonshared mutations (in genes KDM5C, BAP1, and PBRM1)." (PMID 25124064, 2014). "We found a marked decrease in SETD2 levels correlating with higher stages of tumour." (PMID 19698110, 2009). "However, further studies with respect to either transcriptional regulatory or RNA stabilizing effects of m6A mediated by m6A readers will be required to decipher the precise mechanisms through which m6A influences the observed tumor promoting gene expression patterns in SETD2 mutant ccRCC." (PMID 39874221, 2025). "SETD2 mutation may also be associated with tumor growth but not metastasis, which may also allow time for detection at node-negative, non-metastatic earlier stages of disease." (PMID 41228333, 2025). "Notably, while SETD2 is tumor suppressive, the H3K36me2 KMTs are generally oncogenic." (PMID 40462961, 2025). "Furthermore, tumor cell metabolism is a hot topic in recent years, and whether SETD2 or EZH2 influence tumor cell metabolism and its corresponding mechanism needs to be studied." (PMID 40959108, 2025). "Given the significance of SETD2 as a tumor suppressor and SPOP's role in regulating splicing, targeting this axis may offer new therapeutic opportunities in cancer treatment, particularly in cancers like RCC where both proteins are implicated in tumorigenesis and drug resistance." (PMID 40521202, 2025). "Additionally, in mouse models deficient in SETD2—a histone methyltransferase that catalyzes H3K36 trimethylation—tumorigenesis is promoted due to the inhibition of the SIRT1/FOXO signaling pathway, highlighting SIRT1’s role downstream of SETD2 in regulating tumor progression." (PMID 40567502, 2025). "However, VHL mutation, SETD2 mutation and BAP1 mutation had mutational differences of up to 10% between the two groups, suggesting that differential expression of BID mediates differential tumor mutational signatures." (PMID 38767695, 2024). "Another limitation is that we do not establish whether SETD2 loss is tumorigenic or modifies in vivo tumor metastatic properties." (PMID 37418588, 2024). "While SETD2 mutation may initiate loss of H3K36me3, SETD2 mutant cells initially may comprise only a small fraction of the tumor mass, and/or be distributed non-uniformly throughout the tumor." (PMID 37120552, 2023). "Thus, knockdown of SETD2 enhanced erastin-induced tumor cell death via ferroptosis." (PMID 37604811, 2023). "Moreover, many unique mutations were only found in CSF samples, but not in the tumor tissue and plasma samples, which includes FH mutation, SETD2 mutation, WT1 mutation, CDKN2A mutation, CDKN2B mutation." (PMID 36937524, 2023). "Given that tumor mutation load is a consequence of the rates of mutagenesis and DDR, higher TMB and activation of the DDR system might be consistent with a more drastic mutagenesis in patients with deleterious SETD2 mutations." (PMID 37479966, 2023). "In conclusion, the presesnt study revealed that knockdown of the epigenetic molecule, SETD2, significantly increases the sensitivity of ferroptosis inducers which promotes tumor cell death, thereby indicating that SETD2 may be a potential therapeutic target for ccRCC." (PMID 37604811, 2023).
tumor (continued). "We also found that SETD2-deficient cancer cells were more sensitive to transcriptional inhibitors, including the CDK9 inhibitor dinaciclib, which is in accordance with the notion that SETD2 loss–induced upregulation of oncogenic transcriptional programs is required for tumor maintenance." (PMID 36810256, 2023). "In addition, in depth knowledge of splicing regulation by SETD2 (e.g. identifying relevant reader proteins and genes whose splicing is directly affected by SETD2 loss) will be important to uncover the relative contribution of splicing regulation by SETD2 to tumor suppression." (PMID 35661267, 2022). "However, extensive experimental studies are still needed to identify specific regulatory mechanisms of SETD2 on immune-related factors, which could provide new insights into the heterogeneous immune treatment of individual tumor patients." (PMID 36713412, 2022). "However, it was unclear whether the favorable prognosis of SETD2 in LUAD was determined by the tumor or microenvironmental cells." (PMID 36035179, 2022). "To further investigate the relationship between KIRP tumor immunity, we performed the correlation analysis between KIRP immune checkpoint genes (CTLA4, HAVCR2, PDCD1, PDCD1LG2, and TIGIT) and high mutation frequency genes (TTN, MET, KMT2C, PKHD1, SETD2, and KMT2D)." (PMID 36618928, 2022). "No genes were found to be recurrently mutated, however, two tumours had mutations in histone methytransferases (SETD2 and KMT2D) and one also had a mutation in a demethylase (KDM4A), all previously associated with neoplasia and all mutations predicted to be deleterious." (PMID 32698852, 2020). "Interestingly, it was found that SETD2 is a tumor suppressor gene." (PMID 32859239, 2020). "Our model identified mutations in VHL (von Hippel-Lindau), PBMR1, BAP1, MTOR, ATM, SETD2, KDM5C and PTEN (phosphatase and tensin homolog), as well as copy number changes in MLH1, DUSP1 and RANDBP17 as significantly associated with various TF activity changes across tumours." (PMID 28139702, 2017). "Indeed, loci that consistently gain H3K36me3 and 5mC were identified among the cell lines and SETD2 mutated primary ccRCC, but not the SETD2 WT tumor." (PMID 26646321, 2016). "In addition, intra-tumor heterogeneity studies have indicated that SETD2-inactivation may be a late event in cancer development." (PMID 27191891, 2016). "Other molecular features found in this subset of tumours include the enrichment of SETD2 mutations, frequent 1p and 3p losses and aberrant histone methylation (absence of H3K36me3) in cases with concurrent 3p loss and SETD2 mutation." (PMID 27713405, 2016). "SETD2 mutations are independently acquired within multiple parts of the same papillary RCC, suggesting strong selective pressure to inactivate the K36me3 pathway, and SETD2 mutations are enriched in relapsed B-ALL, reinforcing the link between this mutation and tumor progression." (PMID 26646321, 2016). "Given that SETD2 plays a tumor suppressor role and miR-106b-5p has been found responsible for post-transcriptional inhibition of SETD2 in our study, we further explored whether attenuation of miR-106b-5p could suppressed ccRCC cell biologic activity through up-regulation of SETD2." (PMID 25714014, 2015). "Although emerging studies are beginning to provide insight, evidence suggests roles for PBRM1, SETD2, and BAP1 in metabolic regulation and in shaping the tumor immune microenvironment in ccRCC." (PMID 41602827, 2026). "In line with an antitumoural action of DUSP7, a recent work demonstrated that in CRC with SMAD4 deletion, SETD2, a histone methyltransferase, promotes the transcription of DUSP7, leading to inactivation of the RAS/ERK pathway and reduced tumour growth." (PMID 40943262, 2025). "And the effect of SETD2 or EZH2 on tumor microenvironment, especially tumor immune microenvironment needs to de deeply studied." (PMID 40959108, 2025).
tumor (continued). "SPOP facilitates tumorigenesis by targeting and promoting the degradation of tumor suppressors like LATS1, PTEN, SETD2, and others, thus disrupting important signaling pathways such as the Hippo, PI3K/Akt, and cell cycle regulation pathways." (PMID 40521202, 2025). "SETD2 is an HMT that trimethylates H3K36 and regulates DNA methylation, DNA repair, RNA processing, and tumor suppression." (PMID 39765675, 2024). "The most common gene alterations in the primary tumor in RCC are VHL (64%), PBRM1 (36%), SETD2 (20%), and BAP1 (13%)." (PMID 38386122, 2024). "Specifically, modifiers like KDM2A have an oncogenic effect on many cancers, whereas others such as SETD2 and KMT2D play tumor suppressive roles." (PMID 39765675, 2024). "The authors highlight three PKMTs – SETD2, SETD7, and EZH2 – which have been found to suppress tumor growth in various types of cancer." (PMID 38036730, 2023). "This is reasonable given that this chromosome contains four tumor-suppressor genes (VHL, PBRM1, BAP1, and SETD2) that are crucial for cellular survival." (PMID 37842234, 2023). "Stabilization of SETD2 with Palmostatin-B, a drug the prevents de-palmitoylation, led to decreased proliferation of established GBM cell lines and decreased tumor growth in a nude mouse model, consistent with an antiproliferative role for SETD2 in GBM." (PMID 37205197, 2023). "Inactivation of many genes that were functional tumor suppressors in KRAS-driven lung tumors, including Lkb1, Setd2, and Kmt2d, were deleterious in EGFR-driven lung tumors." (PMID 37828026, 2023). "Among these PKMTs, SETD2, SETD7, and EZH2 are relatively well characterized with dominant tumor-suppressive functions." (PMID 38036730, 2023). "Thus, SETD2 may function as a tumor suppressor, and may be a potential prognostic marker in BC." (PMID 37359376, 2023). "To carry out such a multilevel investigation, we measured the mRNA levels of VHL, SETD2, PBRM1 and BAP1 genes by qPCR on the same tumour-normal paired sample set used for our CNV characterisation." (PMID 35586183, 2022). "We showed that by calculating the median transcription values of the four ccRCC tumour suppressors of 3p25 and 3p21 chromosomal loci—VHL, SETD2, PBRM1, and BAP1–, complemented that of the p14ARF, normal and ccRCC tissues can be distinguished." (PMID 35586183, 2022). "SETD2 knockdown significantly upregulated tumor cell apoptosis, attenuated proliferation and migration of LUAD tumor cells, and enhanced radiosensitivity in vitro." (PMID 36035179, 2022). "In humans, the VHL gene is located next to other tumor suppressors (e.g., PBRM1, BAP1 and SETD2) on chromosome 3p." (PMID 35463327, 2022). "According to Cancer Genome Interpreter (CGI) analysis, alterations in SETD2, BAP1, FLT4 and PTEN genes were reported as known drivers in several tumor types, and events in FGFR4 and NSD1 genes were classified as predicted drivers." (PMID 33668731, 2021). "As is known, the short arm of chromosome 3 is the most important region contributing to the pathogenesis of RCC, for the reason that several tumor suppressor genes, like VHL, SETD2, and PBRM1, are identified within this region." (PMID 34218253, 2021). "It is likely that other ccRCC-relevant epigenetic tumour suppressors such as BAP1, SETD2, and KDM5C also influence HIF-α transcriptional outputs." (PMID 32807776, 2020).
tumor (continued). "Additionally, because there are limited GWAS data available on patients who also have tumor molecular data, we did not validate the observed associations between the 8q24 germline variant and VHL tumor mutation nor the association between the EPAS1 germline variant and SETD2 tumor mutation." (PMID 33121461, 2020). "Additionally, in 213 ccRCC, 113 pRCC, and 65 chRCC, of the most commonly mutated HMTs, SETD2, and KMT2C were most frequently mutated in ccRCC and pRCC subtypes, whereas SETD2 was mutated in less than 1.54% of tumor samples and KMT2C did not exhibit mutation in chRCC." (PMID 30755832, 2019). "RQ-PCR analysis of SETD2 in cell lines and normal primary cells showed reduced expression levels in DERL-2/7, indicating tumor suppressor activity." (PMID 31143370, 2019). "Our group have recently identified SETD2 as one of SPOP substrates, which is the major histone H3K36me3 methyltransferase in mammal and a tumor-suppressor in many cancers." (PMID 30237511, 2019). "miR-106b is reported to promote the tumor growth through targeting tumor suppressor genes, such as Pten, Cdkn1a, E2F1, Setd2, Runx3, Smad7, Cdkn1a, and Bim." (PMID 31547867, 2019). "Chromosomal losses and gains regarding 254 driver genes analysed determined losses of SETD2 (43/48) and MAP4 (38/48) at 3p21.31 assigned to Fuhrman grade G1 in 24/26 G1 and 23/26 G1 tumours, respectively, to 17/20 G3 and 13/20 G3 tumours." (PMID 28486536, 2017). "The gene locus 3p21.31 represented by gene losses of SETD2 (43 tumours), KIF9-AS1 (43 tumours) and KIF9 (42 tumours) seems to constitute one locus presenting common Fuhrman grade independent gene losses." (PMID 28486536, 2017). "It is required for gene silencing of the HOXD locus by PRC2, which controls the expression of several critical tumor suppressors such as WIF-1, SETD2, and PTEN." (PMID 28938586, 2017). "The MDR included the CCDC12, NBEAL2, SETD2, KIF9 and KLHL18 genes, of which SETD2 was the most significantly underexpressed in tumour cells." (PMID 27282254, 2016). "At the time of diagnosis, the tumor cells had four distinct SNVs in USP54, GABRA3, KRAS and SETD2, while the relapsed tumor acquired four additional unique mutations in MYH7, NYNRIN, ODZ1 and ZIC3." (PMID 26527318, 2016). "SETD2, a methyltransferase to trimethylate H3K36 of nucleosomes positioned on active genes, has recently been verified to function as a tumor suppressor gene in ccRCC." (PMID 25714014, 2015). "In this minireview, we aim to shed light on the roles of PBRM1, SETD2, and BAP1 in the tumor metabolic and immune microenvironments, and discuss how these functions could benefit the management of advanced ccRCC." (PMID 41602827, 2026). "SETD2, a lysine N-methyltransferase and the sole enzyme responsible for H3K36 trimethylation, has emerged as a promising therapeutic target due to its role in epigenetic regulation and tumor suppression." (PMID 40959108, 2025). "In conventional ccRCC, the loss of chromosome 3p is a common early event, frequently leading to the simultaneous inactivation of key tumor suppressor genes, including PBRM1, BAP1, and SETD2, all of which are involved in chromatin remodeling and histone regulation." (PMID 40940841, 2025). "Although inhibitors targeting SETD2 (e.g., EZM0414) and EZH2 (e.g., tazemetostat) demonstrate antitumor activity in preclinical models, their clinical efficacy remains constrained by drug resistance and tumor microenvironment heterogeneity." (PMID 40959108, 2025). "Age did not impact the effects of inactivation of Stag2, Setd2, Cdkn2c and Rbm10 in either context, further suggesting that age interacts with specific tumor suppressor pathways as opposed to generically weakening the effects of driver mutations." (PMID 41188600, 2025).
tumor (continued). "The JX-594-induced decrease in tumor volume was the most significant in tumors associated with BAP1 mutations as opposed to tumors with VHL, PBRM1, and SETD2 mutations (P < 0.01)." (PMID 40856833, 2025). "Homologous-recombination deficiency (HRD) was positive in this tumor with no mutations in HRD-related genes, which was possibly induced by the copy number deletion of SETD2 gene." (PMID 38167074, 2024). "Therefore, we calculated the Tumor Immune Dysfunction and Exclusion (TIDE) score of TCGA-SKCM samples to explore the impact of SETD2 downregulation on immunotherapy response." (PMID 38843391, 2024). "The most common tumor types were ovarian (n = 23), breast (n = 15), pancreatic (n = 14), and prostate (n = 14); the most frequent enrollment genes were ATM (n = 38), BRCA1 (n = 28), BRCA2 (n = 15), SETD2 (n = 10), and CDK12 (n = 7)." (PMID 38710487, 2024). "However, chromosome 3 is home to multiple tumor suppressors important in many cancers (VHL, SETD2, PBRM1) in addition to BAP1, making it unclear in which cancers BAP1 loss is biologically important." (PMID 39554490, 2024). "Regarding epigenetic regulation, a lack of SETD2 promotes immune evasion by PDAC tumor cells, with neutrophils undergoing the most significant reprogramming toward an immunosuppressive phenotype." (PMID 38982491, 2024). "There are other commonly lost tumor suppressors on this chromosome (VHL, SETD2 and PBRM1)." (PMID 39554490, 2024). "Four tumor suppressor genes map in this region: VHL in 3p.25, PBRM1 (subunit of the PBAF SWI/SNF chromatin remodeling complex), BAP1 (histone deubiquitinase), and SETD2 (histone methyl transferase) in 3p.21." (PMID 36902045, 2023). "This is the first report of a rare tumour harbouring TSC2 and SETD2 variations." (PMID 36510186, 2022). "Although inactivation of Rbm10, Rb1, or Apc did have similar effects on EGFR and KRAS mutant tumor growth, Serine/threonine kinase 11 (Stk11, also known as Lkb1) and SET domain containing 2, histone lysine methyltransferase (Setd2) inactivation had opposite effects in the two oncogenic settings." (PMID 35252550, 2022). "The results showed that SETD2 staining scores were low but not significantly different between tumor and alveolar cells, and that the staining was mainly concentrated in the nuclear." (PMID 36035179, 2022). "In this article, we first report a rare tumour that harbours TSC2 and SETD2 variations." (PMID 36510186, 2022). "In our third patient, the primary tumor showed a combination of TSC1, CUL3, DOT1L and SETD2 gene mutations (but not BAP1), whereas the PM had the same genetic mutations plus BAP1 mutation." (PMID 34885018, 2021). "In the patient without VHL mutation, we found alterations in CUL3, DOT1L, SETD2 and TSC1 in the primary tumor, with the addition of BAP1 gene mutation in its analyzable PMs." (PMID 34885018, 2021). "In the tumor state, these disease-related genes can regulate some famous oncogenes, like SETD2 and STAG1, but not in the normal state." (PMID 34335688, 2021).